SNRPA (small nuclear ribonucleoprotein polypeptide A)
Diseases named in the same sentence as SNRPA in open-access papers (continued):
Sharing a sentence is not in itself a finding about the gene and the disease.
cancer (14 papers, 2008 to 2025). A tumor composed of atypical neoplastic, often pleomorphic cells that invade other tissues. "SNRPA expression in the LUSC cases was linked to the factors of the eastern cancer oncology group (p < 0.05), residual tumor (p = 0.024) as well." (PMID 33552128, 2020). "According to pan-cancer COX analysis, SNRPA was identified as a risk factor for the prognosis of patients with various tumor types." (PMID 39845190, 2024). "In the TCGA pan-cancer cohort study, we performed a thorough analysis of SNRPA expression, and the findings indicated that SNRPA is highly expressed across various tumor types." (PMID 39845190, 2024). "In microinvasive adenocarcinoma and invasive adenocarcinoma (MIA, IAC) subtype sections, SNRPA was more centrally expressed in the cancer region." (PMID 39845190, 2024). "Elevated Small Nuclear Ribonucleoprotein Polypeptide A (SNRPA) can enhance tumor cell growth and proliferation in various cancers." (PMID 35860579, 2022). "Conversely, ectopic SNRPA overexpression promoted an aggressive cancer cell phenotype." (PMID 41354732, 2025). "Further research is warranted to fully unravel the clinical significance of both anti-SNRPA and anti-PLD3 AAbs and their potential implications in different cancer patient populations." (PMID 40768895, 2025). "Intersecting the sets of pan-cancer compensated and toxic genes yields nine high-confidence ARGOS genes, six of which are also frequently amplified: RBM12, RBM14, SNRPA, ZBTB14, POU2F1, and CDKN1A." (PMID 39870664, 2025). "Small nuclear ribonucleoprotein polypeptide A (SNRPA1), a spliceosome component responsible for the splicing reactions of precursor messenger RNAs (pre‐mRNAs), is upregulated in various cancers." (PMID 37277111, 2023). "As small nuclear ribonucleoprotein polypeptide A, SNRPA1 was differentially expressed in most cancer types." (PMID 37277111, 2023). "Additional proteins with significant upregulated scores (BTF3, SNRPA, and NUTF2), which promote cancer in other types of malignances, also lead to lower survival probability in CLL patients, apart from BTF3 that seems to affect survival only during the initial days of disease development." (PMID 39202022, 2024). "Interestingly, the analysis revealed that 7 targets (SF3B1, SF3B3, SNRPA, SNRPE, SNRPF, HNRNPA3 and EFTUD2) are physically interacting proteins within the spliceosome complex, suggesting that JA might regulate the cancer spliceosome to induce tumor-specific cell death." (PMID 28198434, 2017).
tumor (14 papers, 2011 to 2025). "In clear cell renal cell carcinoma (ccRCC), high levels of SNRPA are associated with poor prognosis, as its overexpression leads to increased cell proliferation and tumor aggressiveness." (PMID 41354732, 2025). "SNRPA was associated with microvascular invasion and promoted tumor metastasis in HCC." (PMID 37725627, 2023). "SNRPA has been shown to enhance tumor growth and progression possibly through its involvement in RNA splicing processes that affect gene expression." (PMID 41354732, 2025). "Western blotting analysis corroborated these findings, demonstrating elevated SNRPA protein levels in tumor samples from four representative patients (namely “T1”, “T2”, “T3”, and “T4”)." (PMID 41354732, 2025). "SNRPA expression was predominantly observed in tumor epithelial cells (“Tumor”), with higher expression levels in high-grade tumors (“T-HG”)." (PMID 41354732, 2025). "Further, we studied the prognostic significance of the SNRPA protein expression in early-stage (I+II), low tumor grade (grade I+II), low AFP level (≤400 ng/ml), tumor size ≤ 5cm, Child-Pugh class A, and median/high differentiation subgroups." (PMID 35860579, 2022). "In patients with early tumor stages (stage I+II) and grades (grade I+II), high SNRPA mRNA levels also correlated with poorer OS and RFS." (PMID 35860579, 2022). "Further studies substantiated that LINC01088 interacted with SNRPA and SNRPA mainly mediated the tumor-promoting effect of LINC01088." (PMID 35392763, 2022). "After analyzing the LUAD data of CPTAC, we observed a higher phosphorylation level of SNRPA at the S115 site in the primary tumor than the controls." (PMID 33552128, 2020). "The study showed that high SNRPA expression enhances tumor cell growth in GC as well as poor prognosis in GC patients." (PMID 31581454, 2019). "SNRPA, an oncogene, is closely related to tumor progression." (PMID 39394197, 2024). "Finally, we investigated the correlation of SNRPA expression with the composition of the tumor microenvironment and immunocyte infiltration ratio by the CIBERSORT algorithm and ssGSEA algorithm." (PMID 35860579, 2022). "Furthermore, the expression of SNRPA mRNA gradually increased with the tumor stage and tumor grade increased." (PMID 35860579, 2022). "Furthermore, in patients with early tumor stages (stage I+II) and grades (grade I+II), SNRPA mRNA levels still exhibited significant prognostic value." (PMID 35860579, 2022). "Even though T131 phosphorylation sites of SNRPA protein have been experimentally confirmed, we did not detect the statistical difference in the phosphorylation level at this site between normal and tumor tissues." (PMID 33552128, 2020). "In addition, SNRPA mRNA levels gradually increased with the tumor stage and tumor grade increased." (PMID 35860579, 2022). "We next investigated the potential role of SNRPA in CRPC by evaluating its mRNA and protein expression levels in tumor tissues." (PMID 41354732, 2025). "Certain noncoding RNAs play regulatory roles in this process; for instance, lncRNA CASC19 can bind to small nuclear ribonucleoprotein polypeptide A (SNRPA) and subsequently upregulate the transcription of HK2 and LDHA, thereby driving tumor proliferation and metabolic reprogramming." (PMID 41415548, 2025). "Compared with the NC group injected with NC cells, SNRPA knockout attenuated cisplatin resistance in LUAD cells located in the axillary region of nude mice, as evidenced by reduced luciferase activity, decreased tumor volume, and reduced tumor weight." (PMID 39555714, 2024). "The SNRPA expression was upregulated in HCC and positively correlated with tumor stage and grade." (PMID 35860579, 2022). "Besides, the phosphorylation level at the S115 site of SNRPA protein (NP_004587.1) (p = 0.002), but not the T131 site (p > 0.05), in the primary tumor tissues is higher than that in the normal tissues." (PMID 33552128, 2020).
neurodegenerative disease (1 paper, 2025). A disorder of the central nervous system characterized by gradual and progressive loss of neural tissue and neurologic function. "Tau has been shown to co-aggregate with several core spliceosome components in neurodegenerative diseases, including U1-70K (SNRNP70) and U1A (SNRPA)." (PMID 41205924, 2025).
SNRPA also shares sentences with these, for which no sentence is quoted: colorectal cancer (2 papers); lung squamous cell carcinoma (2); lupus (2); adenocarcinoma (1); autoimmune disease (1); melanoma (1); pancreatic ductal adenocarcinoma (1); Parkinson disease (1); prostate adenocarcinoma (1); small cell lung carcinoma (1).